LPIN3 (lipin 3)
Description:
Magnesium-dependent phosphatidate phosphatase enzyme which catalyzes the conversion of phosphatidic acid to diacylglycerol during triglyceride, phosphatidylcholine and phosphatidylethanolamine biosynthesis therefore regulates fatty acid metabolism.
Synonyms: LIPN3L; SMP2; dJ620E11.2
Tractability: PROTAC: ubiquitination databases record sites on it.
Gene: Protein-coding gene on chromosome 20 (41,340,786 to 41,360,583, forward strand). Ensembl gene ENSG00000132793.
Subcellular location: Nucleus
Subcellular location (Human Protein Atlas): Cytosol
Pathways (Reactome):
Metabolism: Synthesis of PC; Synthesis of PE; Triglyceride biosynthesis
Cell Cycle: Depolymerization of the Nuclear Lamina
Gene Ontology:
Molecular function: phosphatidate phosphatase activity; transcription coactivator activity
Biological process: cellular response to insulin stimulus; fatty acid catabolic process; positive regulation of transcription by RNA polymerase II; triglyceride biosynthetic process
Cellular component: cytosol; endoplasmic reticulum membrane; nucleus
Genetic constraint (gnomAD): Loss-of-function variants: 83 observed, 100.06 expected, observed/expected ratio (o/e) 0.83, 90% interval 0.69 to 1. The upper end of that interval is the gene's LOEUF score, 1, which puts it in group 4 of 6, group 1 being the genes least tolerant of losing a copy. Missense variants: 996 observed, 1,136.9 expected, observed/expected ratio (o/e) 0.88, 90% interval 0.83 to 0.92. Synonymous variants: 418 observed, 462.24 expected, observed/expected ratio (o/e) 0.9, 90% interval 0.83 to 0.98.
Homologues: Orthologues: chimpanzee LPIN3 (98% identical), macaque LPIN3 (96% identical), pig LPIN3 (83% identical), dog LPIN3 (82% identical), rat Lpin3 (82% identical), rabbit LPIN3 (81% identical), mouse Lpin3 (81% identical), guinea pig LPIN3 (78% identical), zebrafish zgc:123305 (51% identical), tropical clawed frog lpin3 (43% identical), Drosophila melanogaster Lpin (38% identical), Caenorhabditis elegans lpin-1 (29% identical). Paralogues in human: LPIN2 (50% identical), LPIN1 (49% identical), AP5Z1 (14% identical).
Diseases named in the same sentence as LPIN3 in open-access papers:
LPIN3 is named in the same sentence as 16 diseases in open-access papers, as found by Europe PMC text mining. Sharing a sentence is not in itself a finding about the gene and the disease. The quoted sentences say what the papers report.
glioma (2 papers, 2023 to 2024). A benign or malignant brain and spinal cord tumor that arises from glial cells (astrocytes, oligodendrocytes, ependymal cells). "Some genes, such as CABP4, DUSP10, LPIN3, were reported for the first time to be associated with glioma." (PMID 37662954, 2023). "Moreover, DUSP11, LPIN3, MTMR11, HDDC2, and PLPPR3 have not been queried for glioma-related studies." (PMID 39830513, 2024).
lipodystrophy (2 papers, 2009 to 2018). A congenital or acquired disorder characterized by abnormal loss or redistribution of the adipose tissue in the body. "Others include suppression of Lpin3, a candidate gene for human lipodystrophy; Kpna2, an importin; and AKAP12, a tumor suppressor." (PMID 18925475, 2009).
acute kidney injury (1 paper, 2025). Sudden and sustained deterioration of the kidney function characterized by decreased glomerular filtration rate, increased serum creatinine or oliguria. "This study aims to elucidate the specific functions of Lipin 3 in the context of acute kidney injury (AKI)." (PMID 40959286, 2025).
cervical cancer (1 paper, 2024). A primary or metastatic malignant neoplasm involving the cervix. "LPIN3 played a crucial role in regulating lipid metabolism, and variable splicing of LPIN3 regulates pyruvate and fatty acid metabolism in cervical cancer." (PMID 38169546, 2024).
COVID-19 (1 paper, 2022). A disease caused by infection with severe acute respiratory syndrome coronavirus 2. "PAP-1 and/or lipin 3-targeting drug compounds may be a potential host-based treatment strategy for COVID-19." (PMID 35874954, 2022).
dementia (1 paper, 2020). Loss of intellectual abilities interfering with an individual's social and occupational functions. "Valproic acid was identified as a potential therapeutic agent that may regulate the mutual switch genes shared among the dementias (PDE4DIP, NEAT1, LPIN3, ADCYAP1, CCDC136, and ITPKB)." (PMID 32471155, 2020).
depression (1 paper, 2025). "Additionally, some depression-associated genes in the South Asian population are linked to diet and metabolism, such as FADS1, FADS2, LPIN3, and SGIP1." (PMID 40075226, 2025).
prostate adenocarcinoma (1 paper, 2021). "From the studies selected from cBioPortal, alterations in the LPIN1, LPIN2 and LPIN3 genes within prostate cancer, prostate adenocarcinoma, castration-resistant prostate cancer and prostate neuroendocrine carcinoma resulted in amplification being the major form of alteration." (PMID 33596934, 2021).
prostate carcinoma (1 paper, 2021). A carcinoma that arises from epithelial cells of the prostate gland. "Results from GEPIA 2 show expression levels of lipin genes varying between patients with and without prostate cancer, with higher significance in LPIN1 and LPIN3." (PMID 33596934, 2021).
type 2 diabetes (1 paper, 2016). "Alterations in lipin-3 protein levels in SAT of participants with type 2 diabetes may be masked by its presence also in the stromal vascular fraction (data not shown)." (PMID 27344312, 2016). "In contrast, SAT LPIN3 expression was significantly increased in the type 2 diabetes (p = 0.018)." (PMID 27344312, 2016).
Williams syndrome (1 paper, 2021). "FKBP6 is associated with the Lipin 3 (LPIN3) gene and the RAD9 checkpoint clamp component A (RAD9A) gene and has been associated with Williams syndrome and Williams-Beuren syndrome, but FKBP6 does not have an advantage in terms of the strength of association with the target disease." (PMID 34966851, 2021).
infection (1 paper, 2021). The state of being infected such as from the introduction of a foreign agent such as serum, vaccine, antigenic substance or organism. "Monoacylglycerol acyltransferases (MOGATs), lipin phosphatidic acid phosphatases (LIPINs), and diacylglycerol acyltransferases (DGATs) are key enzymes in TAG biosynthesis, and all the three types of enzymes were downregulated upon infection, including MOGAT1/2/3, LPIN3, and DGAT1/2." (PMID 33314005, 2021).
LPIN3 also shares sentences with these, for which no sentence is quoted: breast carcinoma (1 paper); cancer (1); prostate neuroendocrine carcinoma (1); tumor (1).